HOXB13 (homeobox B13)
Diseases named in the same sentence as HOXB13 in open-access papers (continued):
Sharing a sentence is not in itself a finding about the gene and the disease.
tumor (continued). "Altogether, our results suggest that upregulation of ciRS-7 abrogates the tumor-suppressive effect of miR-7 on its downstream targets, HOXB13 and therefore promotes downstream p65 phosphorylation in ESCC." (PMID 30082829, 2018). "We next examined DNA methylation in tumour samples at two HOXB13 CpG islands, one spanning the promoter region and exon 1 of the gene, and the second located ~4.5 kb upstream of the HOXB13 transcription start site." (PMID 29259341, 2017). "HOXB13 methylation was also noted to have significant correlation to tumor grade, stage, size, and microvessel invasion." (PMID 26198328, 2015). "The abundant molecular database attached to our tumor collection further enabled us to analyze the role of HOXB13 in tumors of different molecular subtypes, the most common of which is the TMPRSS2:ERG gene fusion." (PMID 25825985, 2015). "Expression of HOXB13 is critical for mammalian prostate development, and likely involved in carcinogenesis of the prostate as a tumor suppressor." (PMID 24497837, 2014). "Distributions of tumor characteristics for categories of HOXB13:IL17BR, MGI, and MGI+HOXB13:IL17BR, and BCI." (PMID 23497539, 2013). "A previous study demonstrated that expression of HOXB13 was controlled in a methylation-dependent manner and its methylation was correlated positively with tumor grade and microvessel invasion." (PMID 22808286, 2012). "The expression of HOXB13 was investigated in tumor specimens from failed androgen ablation therapy and compared to tumors without PSA recurrence." (PMID 20504375, 2010). "HOXB13 was inversely correlated to tumor size (P = 0.0048) and positively correlated to ER (P = 0.0022) and HER2 levels (P = 0.0023)." (PMID 20649975, 2010). "The expression level of HOXB13 from all normal tissues was averaged to acquire a relative expression level of HOXB13 for each tumour." (PMID 15928669, 2005). "Importantly, pharmacological inhibition of p300 and CBP blocks HOXB13-loss-driven lipogenesis, reduces MMP expression, and decreases cell migration in vitro and tumor metastasis in vivo." (PMID 41277556, 2025). "Modules 9 and 10 include HOXB13 and HOXD10, both of which belong to the HOX gene family and are associated with cell migration and invasive capacity, and both transcription factors showed upregulation in Il1r2−/− tumor cells." (PMID 40767963, 2025). "Importantly, FOXA1 reprograms the AR cistrome in PCa and its overexpression, either alone or in combination with HOXB13, can push the AR towards a more tumor-like cistrome." (PMID 40833121, 2025). "Second, further experimental validation is required to clarify whether the anti-tumor effects of si-HOXB13 are indeed mediated through this signaling cascade." (PMID 41023726, 2025). "In addition, H&E staining of lung tissues revealed metastatic tumor foci in both groups; however, the number of lung metastases was markedly lower in the sh-HOXB13 group." (PMID 41023726, 2025). "Immunohistochemical staining of NPC tumor tissues further confirmed HOXB13 overexpression." (PMID 41023726, 2025). "Third, considering the established link between tumor cell stemness and therapeutic resistance, future investigations are warranted to explore whether targeting HOXB13 could modulate resistance mechanisms in NPC." (PMID 41023726, 2025). "While functional studies are needed to demonstrate the impact of the mutation, clinical data of patients support the hypothesis that HOXB13 X285K could contribute to dissemination of tumor cells." (PMID 41188766, 2025). "Interestingly, HOXB13 is highly expressed in circulating tumor cells and predicts early death following AA treatment." (PMID 38891761, 2024). "The role of this candidate cofactor in HOXB13 proliferative activity was tested using the xCELLigence system, which uses cellular impedance to continuously measure the number, size and surface attachment strength of adherent tumor cells." (PMID 36611993, 2023).
tumor (continued). "Since this tumor displays HOXB13 upregulation, the immunohistochemical detection of this protein may be used in routine practice for the distinction from other tumor types." (PMID 38074692, 2023). "For all 72 cases, HOXB13 immunostaining in tumor glands, assessed in comparison to the intensity of luminal secretory cells of benign adjacent prostatic glands, was characterized by intra- and inter-tumor heterogeneity." (PMID 37894380, 2023). "Notably, low HOXB13 expression was significantly associated with MIBC, higher tumor stage, higher tumor grade, and metastatic risk." (PMID 37627895, 2023). "In addition, low HOXB13 expression was significantly associated with MIBC, higher tumor stage (pT2–pT4) and grade (grades 2 and 3), and metastatic risk." (PMID 37627895, 2023). "However, the precise role of HOXB13 in prostate carcinogenesis still remains a matter of debate, as it is considered both an oncogene and a tumor suppressor gene, with direct implication in modulating androgen responsiveness." (PMID 37894380, 2023). "HOXB13 has a protective effect against tumor proliferation in RCC, and a reduction in the expression of HOXB13 via hypermethylation of the DNMT3B-HOXB13-C-myc signaling axis has been associated with tumor proliferation and metastasis in RCC." (PMID 37434131, 2023). "Taken together, it would seem that high levels of HOXB13 expression in tumours may drive initial tumour growth but suppress subsequent metastasis." (PMID 35080776, 2022). "Indeed, homeobox B13 (HOXB13) was the only DEG found to be significant in both tumor versus NAT analyses that was discordant for direction of effect." (PMID 36077675, 2022). "LvCaP-1 expressed NKX3-1, HOXB13 (mutated G84E), FOLH1, KLK2, and KLK3, but with only a low level of PSA secretion (i.e., serum PSA of 1.4 ± 0.4 ng/mL/g tumor)." (PMID 33724955, 2021). "Moreover, HOXB13 is identified as either a tumor suppressor or oncogene in different tumor types 13-15." (PMID 33897880, 2021). "HOXB13 deletion demonstrates that the tumor-suppressive activity of MEIS1 is dependent on HOXB13." (PMID 32553107, 2020). "Importantly, inclusion of HOXB13ko lines enabled determination of HOXB13-associated gene regulation as well as identification of significant changes between LV-MEIS1 and control cells that were HOXB13-independent and thus unrelated to tumor suppression." (PMID 32553107, 2020). "However, there remain significant gaps in our understanding of how MEIS proteins suppress tumor progression and the role of HOXB13 in MEIS-mediated tumor suppression." (PMID 32553107, 2020). "However, their locations in the MEIS-interacting domains of HOXB13 point toward changes to MEIS–HOXB13 complexes and/or transcriptional regulation as leading to decreased tumor suppression and enabling malignant transformation." (PMID 32553107, 2020). "Nude mice inoculated with HCT116/sh-HOXB13 cells had an increased tumor load compared with control shRNA-transfected xenograft tumors at 20 days (67.5 ± 6.6 vs 40 ± 5.4, respectively, P < 0.05) and 30 days (300 ± 36.74 vs 130.8 ± 15.28, respectively, P < 0.05) after inoculation." (PMID 31815008, 2019). "Our results were in contrast to Tatangelo’s finding that HOXB13 is downregulated in normal tissue compared to tumor tissue, which might be explained by differences in the study populations and specimens." (PMID 31815008, 2019). "Therefore, it is possible that the in vitro expression of HoxA10, HoxA11, and HoxB13 differs from that of tumor tissues in vivo." (PMID 31137902, 2019). "Morphological variants of DAC, which is located adjacent to Gleason pattern 4 DACs, also showed expression of HoxB13 in columnar cells of Gleason pattern 3 DACs and singly scattered tumor cells or those comprising large nests with central comedo-type necrosis of Gleason pattern 5 DACs." (PMID 31882852, 2019). "Most of the normal samples presented higher HOXB13 expression than the RCC tumor samples." (PMID 31815008, 2019).
tumor (continued). "For HoxB13, the expression patterns within each tumor subtype and Gleason pattern differed." (PMID 31882852, 2019). "In addition, high level of HoxB13 expression showed a tendency toward tumor volume more than 5cc (P = 0.056), and frequent intact PTEN expression (P = 0.065)." (PMID 31882852, 2019). "In summary, cellular and animal experiments have shown that HOXB13 may be an important tumor suppressor gene and that low HOXB13 expression plays a critical role in the pathogenesis and progression of RCC." (PMID 31815008, 2019). "Additionally, HOXB13 was revealed to be downregulated in only RCC tumor tissue compared to normal tissues." (PMID 31815008, 2019). "In addition, HoxB13 was expressed in tumor cells that exhibited tubular structures or growth patterns equivalent to Gleason pattern 5 of AAC." (PMID 31882852, 2019). "This study has shown that HOXB13 expression does not differ between tumour tissue of G84E variant carriers and non-carriers." (PMID 29259341, 2017). "At least 50% of tumor cells overexpressed HOXB13 in the 10 samples." (PMID 20504375, 2010). "Expression of HOXB13 was located exclusively in the nuclei of the tumor cells." (PMID 20649975, 2010). "Therefore, to identify whether FOXA1 and HOXB13 are colocalized with AR in the regulatory regions (−5 kb/+2 kb from TSS) of the DE-lncRNAs, we used previously published FOXA1 and HOXB13 ChIP-seq data in PCa tumor samples." (PMID 37140987, 2023). "In addition, we found that overexpression of ciRS-7 abrogated the tumor-suppressive roles of miR-7 and reactivated the HOXB13-mediated NF-κB/p65 pathway in ESCC through a systematic and comprehensive functional analysis followed by a series of tumor xenograft animal assays." (PMID 30082829, 2018). "Furthermore, HOXB13 methylation correlated positively with tumor grade and microvessel invasion." (PMID 29299153, 2017). "Additionally, those studies reported that different populations of HOXB13-negative and HOXB13-positive cells could be observed in the same tumor." (PMID 28050579, 2016). "Conversely, Il1r2−/− tumor cells demonstrated higher specificity for regulons controlled by IRF7, HOXB13, and JUND." (PMID 40767963, 2025). "Pearson correlation analysis comparing the expression of each marker in normal prostate and in tumor revealed a significant correlation between HOXB13 and PSMA for normal prostate (r = 0.684, P = 0.001) and tumor (r = 0.501, P = 0.028)." (PMID 38936974, 2024). "HOXB13 and FOXA1 are enriched at tumor-promoting genes and can open the chromatin to generate a permissive chromatin landscape to support AR activities in androgen-dependent and independent states." (PMID 38201640, 2024). "Among the most overexpressed genes in tumor cells compared to normal tissue were the transcription factors HOXB9, SIM2, ZIC5, SP8, TFAP2A, FOXE1, HOXB13, and SALL4; the cancer testis antigen CT83; and the cytokine IL23A." (PMID 37228492, 2023). "A stable knock-out of HOXB13 by using CRISPR/Cas 9 led to a reduced PSMA expression, an increased tumor weight and a reduced metastatic potential." (PMID 37569712, 2023). "We observe an enrichment for Fra1, Fra2, JunB, Atf3 and AP-1 in tumours with Gleason pattern 3 whereas tumours with Gleason pattern 4 show an enrichment for FOXA1, HOXB13 and CDX2." (PMID 34911933, 2021). "Recently, HOXB13, another member of the homeobox gene family, was found to be downregulated in RCC via hypermethylation and to play a tumor suppressive role in RCC20." (PMID 33795652, 2021). "We observe that patients with PRAD tumours have higher expression of FOXA1 and HOXB13 compared to the normal prostate tissue and poor survival is associated with high FOXA1 expression." (PMID 34911933, 2021). "The resulting 157 DEGs represent genes that are direct targets of MEIS1 only when HOXB13 is present and therefore represent prioritized candidates to elucidate the mechanism of MEIS1-dependent tumor suppression." (PMID 32553107, 2020).
tumor (continued). "HOXB13 can directly upregulate a series of genes related to metastasis and drug resistance by directly binding to EZH2, promoting tumor progression and predicting poor prognosis." (PMID 33299862, 2020). "Analysis of ChIP sequencing data (GSE56288) for the recruitment of HOXB13 and AR to the vicinity of the CIT/STK21 revealed overlapping peaks, consistent with our original selection for tumor-specific ARBS." (PMID 31273254, 2019). "The results above indicated that the DNMT3B-induced downregulation of HOXB13 mediates methylation and regulates C-myc expression via β-catenin/TCF4 signaling, enhancing tumor progression and resulting in a poor prognosis." (PMID 31815008, 2019). "Downregulation of HoxA10, HoxA11, and HoxB13 in KPA cells is unexpected, because these Hox genes act as tumor-promoting genes in several types of cancers." (PMID 31137902, 2019). "Tissue sample analysis showed that HOXB13 was differentially expressed between normal and only RCC tumor tissues." (PMID 31815008, 2019). "For example, the hypermethylated homeobox gene HOXB13 overexpression and gene-body hypermethylation was observed in UCEC and four other tumor types including BRCA, LUAD, LUSC, and STAD." (PMID 30097071, 2018). "Scenario 3 included HOXB13 expression, preoperative PSA, clinical tumor stage (cT stage) and Gleason grade obtained on the prostatectomy specimen." (PMID 25825985, 2015). "The interaction between HOXB13 expression and treatment effect was statistically significant for DRFS (P = 0.035; multivariate model adjusted for tumor size and HER2 status)." (PMID 20649975, 2010). "Analysis of possible relationships between HOXB13 protein expression and different tumor variables revealed correlations to HER2, ER and tumor size." (PMID 20649975, 2010). "Similar to FOXA1, overexpression of HOXB13 in an non-neoplastic prostate cell line pushed the AR cistrome to a more tumor-like profile." (PMID 40833121, 2025). "Earlier, we reported that HOXB13 is an epigenetic target of BRD4 in CRPCs, and suppression of HOXB13 expression by the BET inhibitors JQ1 or MA4-class of compounds induces apoptosis and significantly inhibits PC xenograft tumor growth." (PMID 38730575, 2024). "Among the most overexpressed genes in tumor cells compared to normal tissue are genes coding for transcription factors (HOXB9, SIM2, ZIC5, SP8, TFAP2A, FOXE1, HOXB13, and SALL4), cancer testis antigens (CT83), and cytokines activating regulatory Th17 cells (IL23A)." (PMID 37228492, 2023). "We cannot entirely rule out that the low AR/NKX3.1/HOXB13 tumor cells at baseline were selected for by enza treatment." (PMID 36109521, 2022). "Like HOXD13, HOXB13 expression is restricted to the distal colon and rectum (generally at higher levels than HOXD13), and it is expressed in HPs as well as all other tumor types, with levels in distal-colon tumors that are far higher than those in their proximal-colon counterparts." (PMID 33423702, 2021). "The inverse association between MEIS1 expression and AR extended further to HOXB13 expression, indicating that in a subset of primary PCa, decreased expression of MEIS1 may be necessary for AR and HOXB13 to drive tumor development and progression." (PMID 32681068, 2020). "In the present study, a signature for BRCA radiotherapy sensitivity prediction was developed based on the expression of six characteristic DEGs, including HOXB13, NKX2-2, ADAMTS20, LOC284930, ACTL8 and LOC101928978, in BRCA tumor samples compared with their paracancerous samples for the first time." (PMID 33179733, 2020). "Also, the observed upregulation of its adjacent genes (genomic co-ordinates), HOXB13 and PRAC2 allude to possible co-regulatory mechanisms in RSCC, emphasizing their differential roles in proliferation and tumor growth potential within the two tumor types." (PMID 32293332, 2020). "In the almost all of cases, HoxA13 and HoxB13 were expressed in the nucleus of tumor cells, with concomitant non-specific cytoplasmic staining." (PMID 31882852, 2019).
tumor (continued). "HOXB13 was predicted to act as the downstream target of miR-728 through complementary binding sequence in the 3′-UTR (3′-untranslated region) and promotes tumor cell proliferation and metastasis in several human cancers." (PMID 30082829, 2018). "Thus, HBXIP/HOXB13 axis efficiently circumvents TAM by converting ER-α-dependent cell growth to IL-6-dependent, providing alternative proliferative stimuli for tumor cells and making the cells continue to grow." (PMID 29471853, 2018). "Expression of HOXB13 was upregulated in ESCC tumor tissues than that in the paired non-cancerous tissues and correlated negatively with miR-7." (PMID 30082829, 2018). "Among both carriers and non-carriers, HOXB13 protein expression was generally a bit higher in the cytoplasm of tumor cells compared to benign glands." (PMID 28186998, 2017). "In summary, this study has demonstrated that HOXB13 gene and protein expression do not differ in the tumours of G84E carriers and non-carriers." (PMID 29259341, 2017). "Seventeen (30 %) of 56 primary RCC tumor samples examined showed tumor-specific methylation of HOXB13 and none in the adjacent normal kidney tissue samples." (PMID 26198328, 2015). "We used immunohistochemistry to analyze protein levels of HOXB13 in tumor samples from 912 postmenopausal node-negative breast cancer patients randomized to adjuvant tamoxifen therapy or no endocrine treatment." (PMID 20649975, 2010). "Expression of HOXB13 is either lost or diminished in 26 out of 42 valid tumours (62%), while expression of TCF4 RNA is not correlated with HOXB13 expression." (PMID 15928669, 2005). "Importantly, none of the CCS1477-treated HOXB13-KD mice developed tumor metastasis, strongly supporting the idea that CCS1477 treatment eliminated HOXB13-KD-induced metastasis." (PMID 41277556, 2025). "In five cases with insufficient tumor material and in another case with no match in DNA methylation profiling, immunohistochemistry with antibodies against HOXB13 and MYCN proteins were used as surrogate markers for the methylation types of SP-MPE or SP-EPN-MYCN, respectively." (PMID 39713042, 2024). "Interestingly, Sample_15, a Gleason pattern 4 tumour, shows high enrichment for FOXA1, HOXB13 and CDX2, followed by Fra1/2, Atf3, JunB and AP-1 binding sites enriched in Gleason pattern 3 tumours, suggesting a transitionary state between the two regulatory states." (PMID 34911933, 2021). "Interestingly, we observed an enrichment for FOXA1 and HOXB13 in Gleason pattern 4 tumours independent of their ERG accessibility." (PMID 34911933, 2021). "Having established the tumor-suppressive capability of MEIS1 and its ability to act as a putative HOXB13 cofactor in PrECs, we next sought to test whether MEIS-mediated growth suppression is HOXB13-dependent." (PMID 32553107, 2020). "HOXB13 was present in the nuclei of most tumor glands in both carriers and non-carriers." (PMID 28186998, 2017). "However, for patients with a high or intermediate HOXB13 tumor expression, tamoxifen did not prolong the DRFS compared with the untreated patients (hazard ratio = 0.88, 95% confidence interval = 0.47 to 1.65, P = 0.69)." (PMID 20649975, 2010). "This may explain why HOXB13 did not inversely correlate with the expression of TCF4 in patient tumour samples in our RNA analyses." (PMID 15928669, 2005). "Our data showed the absence of expression of HOXA13, HOXB13, HOXC13 and HOXD13 in the normal mucosa, a slight increase in expression in the transitional mucosa, up to in many cases over-expressed in the tumor." (PMID 30541551, 2018). "Although we have not found other reports that have compared the HOXB13 expression in different ETS subtypes, our results are in agreement with other studies comparing carcinomas with non-tumor samples." (PMID 28050579, 2016).